CD79A (CD79a molecule)
Diseases named in the same sentence as CD79A in open-access papers (continued):
Sharing a sentence is not in itself a finding about the gene and the disease.
lymphoma (continued). "The lymphoma had a striking LBCL-like morphology; the neoplastic cells were strongly positive for CD30 and CD15, showed markedly diminished expression of the B cell program (negativity for CD20, CD79a, OCT2, BOB1, and CD19), as well as for CD45, CD23, and PDL1." (PMID 37530791, 2023). "Importantly, the WHO-HEM5 excludes the use of CD79a in B-lineage assignment if the aberrant blast population meets the criteria for T-lineage assignment due to the frequent aberrant expression of CD79a in T-lymphoblastic leukemia/lymphoma." (PMID 40075717, 2025). "Thus, we suggest that the overactivation of BCR-related genes such as CD79A, CD79B, and LAMTOR4 as the shared overexpressed genes among DLBCL, pSS peripheral, and SGs could be involved in pSS progression into lymphoma and probably be responsible for the failure of Rituximab therapy." (PMID 37176092, 2023). "Generally speaking, CD20+ malignant T lymphoma cells are positive for CD3 and monoclonal TCR gene rearrangements and negative for CD10, CD19, or CD79a and clonal IgH gene rearrangements." (PMID 40270601, 2025). "Immunohistochemistry stains of lymphoma cells were positive for CD20, CD79a, CD10, MUM1, BCL6, C-MYC, and negative for BCL2, cyclin D1, CD5, and CD3." (PMID 36120205, 2022). "Negativity for leukocyte common antigen (LCA) and other lymphoid markers (CD3, CD20, CD7, CD4, CD79a, CD30, CD68, PAX5, ALK1, and TdT) rules out malignant lymphoma." (PMID 29914385, 2018). "The lymphoma cells usually express CD45 without expression of pan-B markers (CD19, CD20, CD22 and CD79a) or T/NK cell markers." (PMID 25613729, 2015). "Immunohistochemical analysis revealed that the lymphoma cells were positive for CD20 and CD79a, but negative for CD3." (PMID 26435907, 2015). "Most lymphoma cells are positive for CD20 and CD79a but can be negative in cases with plasmacytic differentiation." (PMID 25613729, 2015). "The immature cells in B-acute lymphoblastic leukemia/lymphoma can be small or medium sized with scant or moderate cytoplasm and typically express B-cell markers such as CD19, cytoplasmic CD79a, and TdT without surface light chains." (PMID 23533894, 2013). "In our case, tumor cells did not express cytokeratins, vimentin but the expression of CD79a, CD20 and bcl2 protein was clearly positive, which enabled us to retain the diagnosis of lymphoma." (PMID 24319526, 2013). "In patients treated with an agent targeting CD22, CD24 may serve to identify normal and neoplastic B cells; however, not all cases of B-lymphoblastic leukemia/lymphoma are CD24 positive, so analysis for additional B cell markers, such as CD79a, may be helpful." (PMID 40227608, 2025). "This lymphoma arose in a 22-year-old immunocompetent male with an isolated mediastinal mass, showed MGZL-like morphology and immunophenotype (strong CD30 and CD20 expression; negative for CD15, CD79a, OCT2, and BOB1), and demonstrated a PMBL-like GE with Lymph3Cx analysis." (PMID 37530791, 2023).
Sepsis (67 papers, 2011 to 2026). Sepsis is defined as life-threatening organ dysfunction caused by a dysregulated host response to infection. "In this study, the key genes downregulated during sepsis also encoded proteins responsible for the immune response, including the expression of antigen-presenting cells, the regulation of cytokine production, and the activation of B and T lymphocytes (i.e., CD79A, HLA-DQB2, PLD4, and CCR7)." (PMID 37298316, 2023). "The expression of some of those genes (FCRL1, TNFRSF13C, CD22, CD79A, POU2F2) continue to be upregulated during sepsis recovery stage too." (PMID 38898888, 2024). "In addition, we identified key genes that were upregulated in sepsis, namely, S100A8, S100A9, and CR1, as well as those that were downregulated, namely, CD79A, HLA-DQB2, PLD4, and CCR7." (PMID 37298316, 2023).
breast cancer (45 papers, 1977 to 2025). A primary or metastatic malignant neoplasm involving the breast. "Furthermore, a breast cancer stem cell subpopulation strongly associated with poor prognosis has been identified, which has been defined as CD79A+CD24-PANCK+-BCSCs subpopulation." (PMID 38066053, 2023). "Notably, the CD79A+CD24-PANCK+-BCSCs subpopulation with poor breast cancer prognosis in this study was strongly associated with CD8+ T-cell exhaustion and the formation of an immunosuppressive tumor microenvironment." (PMID 38066053, 2023). "The genes CXCL9, IL7R, CD79A, and CTSW were selected for their significant associations with overall survival (OS) and recurrence-free survival (RFS) in breast cancer patients." (PMID 40725191, 2025). "Survival analysis indicated the increased expression of CD79A and CD96 was significantly associated with favorable relapse-free survival (RFS), overall survival (OS) in breast cancer." (PMID 34526986, 2021). "34% of the breast cancer samples examined (n = 60 total) were positive for CD79a+ infiltrating myeloid cells." (PMID 24146823, 2013). "We observed similar myeloid cells expressing CD79a in the genetically engineered MMTV-PyMT metastatic mammary cancer model on the FBV/N mouse strain." (PMID 24146823, 2013). "Additionally, CD79A gene was searched out in the Genecards database as keywords “breast cancer stem cells” and our subsequent data analysis also revealed that it is indeed an important gene involved in breast cancer cell stemness." (PMID 38066053, 2023). "Recent studies in veterinary oncology have begun to explore the presence and role of B cell infiltration in the tumor microenvironment, revealing that CD79a and CD20 positive B cells are found in feline oral squamous cell carcinoma and canine mammary tumors." (PMID 41040928, 2025). "Patients with breast cancer who had low levels of expression of the genes CD19, CD79A, IFIT5, MS4A1, and TCL1A had shorter disease-free survival times." (PMID 37684436, 2023). "PLA2G2A was also positively correlated with the CD45 antigen PTPRC, B-cell marker CD79A, and CD8 T cell marker CD8A in breast cancer patients." (PMID 36357424, 2022). "CD79A, SERPINH1, KCNJ5 and TMEM14C exhibited breast cancer subtype–independent overall survival differences." (PMID 25572802, 2015). "Interestingly, expression of some immune cell genes and DVL-1 uniquely correlated with luminal breast cancer, such as CD19, CD79A, CD8B, CCR7, CD1C, and STAT5B." (PMID 34659647, 2021). "In contrast, in the genetically engineered non-metastatic BrCa1 mammary cancer model (on a mixed mouse strain), the expanded myeloid cells did not upregulate CD79a (CD79-11)." (PMID 24146823, 2013). "Furthermore, the complex interplay identified between the CD79A+CD24-PANCK+-BCSCs subpopulation and exhausted CD8+ T cells not only offered an avenue for improving prognosis in breast cancer but also emphasized the importance of breast cancer stem cells in the immunosuppressive microenvironment." (PMID 38066053, 2023).
lymphopenia (44 papers, 2013 to 2025). Reduction in the number of lymphocytes. "CD4 T cells and CD79a+ B cells were shown to account for the lymphopenia, while CD4+CD8+ T cells were increased at 7 dpi in domestic pigs, and no T-cell activation was detected in terms of Ki67 and T-bet expression." (PMID 38419627, 2024).
lupus nephritis (43 papers, 2012 to 2026). Glomerulonephritis in the context of systemic lupus erythematosus. "Comparison of B lineage markers confirmed that CD79a provides far superior sensitivity for interstitial B cells compared to CD19, establishing it as the requisite anchor for B cell burden assessment in FFPE lupus nephritis tissue." (PMID 41958646, 2026).
colorectal cancer (41 papers, 1982 to 2025). A primary or metastatic malignant neoplasm that affects the colon or rectum. "In conclusion, our study of the liver metastasis of patients with colorectal cancer showed that high stromal infiltration of CD79A+ B cells and high stromal infiltration of K/L+ plasma cells might be favourable prognostic biomarkers after surgery for CRLM." (PMID 32195184, 2020).
melanoma (41 papers, 1974 to 2026). A malignant, usually aggressive tumor composed of atypical, neoplastic melanocytes. "Importantly, CD79a and CD74 have been associated with anti-tumor response in OPSCC and in melanoma patients, respectively." (PMID 38893183, 2024). "Other pertinent negative immunostains include hematolymphoid markers (CD45, CD3, CD20, CD79a), myoid markers (smooth muscle actin (SMA), desmin), vascular markers (CD31, CD34), epithelial markers (EMA, keratins), melanoma markers (melanA, SOX10, HMB45, S100), and other markers (ALK, CD30)." (PMID 40563703, 2025). "The pertinent negative markers include histiocytic markers (CD163, CD14, CD1a, langerin), FDC markers (CD21, CD23, CD35, clusterin, CXCL13), hematolymphoid markers (CD45, CD3, CD20, CD79a), vascular markers (CD31, CD34), melanoma markers (melanA, SOX10, HMB45, S100), and others (ALK, CD30)." (PMID 40563703, 2025).
Thrombocytopenia (39 papers, 2012 to 2025). A reduction in the number of circulating thrombocytes. "Our data indicated that HIV-infected DLBCL patients had high incidence of bone involvement and thrombocytopenia, which might relate to low expression of CD20 and CD79a on histopathology." (PMID 36358798, 2022).
depression (37 papers, 2013 to 2025). "In addition, there are few studies on IL7R, IGLL5, and CD79A in depression." (PMID 36561317, 2022).
parasitic infections (37 papers, 2009 to 2025). "Overall, the evidence gathered from the literature underscores the significance of CD79A in parasite resistance and highlights its potential as a target for therapeutic intervention in combating parasitic diseases in sheep and other susceptible hosts." (PMID 40150341, 2025). "The CD79A gene, encoding the Ig-alpha protein of the B-cell antigen receptor complex, emerges as a key player in the immune response against parasitic infections in sheep." (PMID 40150341, 2025). "Understanding the molecular mechanisms underlying CD79A-mediated immune modulation provides valuable insights into host–parasite interactions and may pave the way for the development of novel strategies for controlling parasitic infections." (PMID 40150341, 2025). "This highlights the multifaceted role of CD79A in orchestrating immune responses against parasitic infections and the intricate interplay between host and pathogen." (PMID 40150341, 2025). "CD79A, integral to B-cell activation and antibody production, plays a key role in the immune response against parasitic infections." (PMID 40150341, 2025).
B-cell lymphoma (34 papers, 2009 to 2026). "Despite the absence of systemic symptoms and a vitreous sample of low cellularity, diagnostic pars plana vitrectomy confirmed large B-cell lymphoma via immunophenotyping (CD20, CD79a and PAX5)." (PMID 41948257, 2026). "CD79a and CD79b form the heterodimeric signaling component of the B-cell receptor, with CD79b being nearly universally expressed in mature B-cell lymphomas and normal B cells." (PMID 41383509, 2025). "Recently, the novel CD19CAR-T cells incorporated with B-cell costimulatory molecules of CD79A/CD40 demonstrated superior antitumor activity in the B-cell lymphoma model compared with CD28 or 4-1BB." (PMID 36505428, 2022). "Increased CD79a expression was also observed in B cell lymphomas in cattle with BLV as compared to healthy cattle." (PMID 36477266, 2022). "To date, a number of biomarkers with a diagnostic value for each B-cell lymphoma subtype have been determined: BCL2, BCL6, CD10, CD21, and STMN1 in FL; D1 and SOX11 in MCL; FOXP1 and MUM1 in ABC-DLBCL; CD10, BCL2, BCL6, LMO2, and GCET1 in GC-DLBCL; and CD30, CD15, EBV, BOB1, OCT2, and CD79a in HL." (PMID 37894763, 2023). "Several studies indicated that CD79A was connected with aggressive hematological malignancy, could be a popular marker in the detection and treatment of hematopathy such as Hodgkin’s lymphoma and B-cell lymphoma." (PMID 33993869, 2021). "Most B cell lymphomas are positive for one or more B cell markers including CD19, CD20, CD79a, or PAX5." (PMID 39055348, 2024). "In B-cell lymphoma, the most frequent aberrancies were MHC II- (53%), CD3+/CD21+ (41%), CD34+ (24%), and CD79a- (24%)." (PMID 37908841, 2023). "The most represented aberrancies in B-cell lymphoma were MHCII- (9/17, 53%), CD3+/CD21+ (7/17, 41%), CD34+ (4/17, 24%), CD79a- (4/17, 24%), while CD3+/CD21+ (5/8, 63%), CD4-/CD8- (4/8, 50%), CD45- (4/8, 50%), CD5- (4/8, 50%) were expressed in T-cell lymphoma." (PMID 37908841, 2023). "A puncture biopsy of the right mammary gland tumor was performed again, and it showed CD20 (+), CD79a (+), CD3 (-), CD19 (100%+), PD-1 (-), PD-L1 (-), and Ki-67 (70%+), followed by a pathological diagnosis of high-grade B-cell lymphoma." (PMID 36032118, 2022). "Bone marrow tissue biopsy was performed, showing CD20 (+), CD79a (+), CD3 (–), CD5 (-), CyclinD1 (-), Bcl-2 (+), Bcl-6 (-), CD10 (-), MUM-1 (+), and Ki67 (+>50%), and a pathological diagnosis of high-grade B-cell non-Hodgkin lymphoma was made." (PMID 36032118, 2022). "The CD20, CD79a, and PAX5 are commonly used to identify B cell lymphomas, while CD3 is a specific marker for T cell lymphoma." (PMID 36157173, 2022). "The pathological diagnosis was still high-grade B-cell lymphoma, with CD20 (+), CD79a (+), CD3 (-), and Ki-67 (80%+)." (PMID 36032118, 2022). "Diffuse large B-cell lymphoma cells generally express pan B cell markers such as CD20, CD19, CD22, CD45 and CD79a; seventy percent of tumor cells express BCL-6 protein; CD10 is expressed in 30 to 60% of cases." (PMID 25294404, 2014). "It is possible to misdiagnose the current case as a large B-cell lymphoma expressing CD19, CD20, and CD79a." (PMID 24066244, 2013). "To verify the identity of the tumor implanted, we used immunohistochemistry to evaluate the presence of B cell lymphoma markers CD20 and CD79a." (PMID 22848504, 2012). "Immunohistochemical analysis demonstrated that the tumor cells were positive for B cell lymphoma markers, CD20 and CD79a." (PMID 22848504, 2012). "As a B cell lymphoma, MCL is characterized by the presence of characteristic B cell expression patterns with high (> 90%) expression of CD5, CD19, CD20, CD21, CD22, CD43, CD79a, sIg, and cIg, and low (< 10%) expression of CD10 and CD23." (PMID 27119356, 2016). "The CD20, CD79a, and CD10 are used to determine the B cell lymphoma." (PMID 20062547, 2009).
B-cell lymphoma (continued). "Histologically, PMBCL overlaps with nsHL in that PMBCL expresses B-cell markers (such as CD19, CD20, CD22, and CD79a) but lacks expression of surface or even cytoplasmic immunoglobulin (Ig), despite expression of the Ig co-receptors/antigens (such as CD79a), unlike other B-cell lymphomas." (PMID 36909112, 2023). "In B-cell lymphomas, tumour cells showed cytoplasmic expression of CD20 and CD79a and were negative to CD3." (PMID 40045318, 2025). "Although these B-cell lymphomas did not express CD20, they stained positively for alternative markers such as MUM1, CD79a, and PAX5." (PMID 40287766, 2025). "Immunohistochemical stain revealed that tumor cells were diffusely positive for CD20, CD79a, bcl-2, and negative for CD3, CD5, CD10, cyclin D1 and bcl-6, which excludes the possibility of low grade B-cell lymphoma other than EMZL." (PMID 26111022, 2015).
gastric cancer (32 papers, 2009 to 2025). A primary or metastatic malignant neoplasm involving the stomach. "In addition, some B-cell markers sometimes correspond to a poorer prognosis, such as CD19 (which was found to be associated with a poor prognosis in studies of breast and gastric cancers) and CD79a expression on immature myeloid cells, contributing to their tumour-promoting effects." (PMID 36890557, 2023). "Our results showed that CLDN10 expression significantly correlated to the expression of B cells (CD19, CD79A) and Tfh cells (BCL6, IL21) markers, which indicated a potential mechanism for CLDN10 to regulate B cell function in gastric cancer." (PMID 34721537, 2021).
lung carcinoma (27 papers, 2006 to 2025). "In lung cancer, CD79A expression is primarily associated with regulating the tumor immune microenvironment." (PMID 40881693, 2025). "FCRLA and CD79A were highly expressed in lung cancer cells, whereas RASGRP2 was expressed at low levels." (PMID 40881693, 2025). "CD79A is altered in many cancers, including lung cancer (2017)." (PMID 36313439, 2022). "Importantly we found that CD79a was significantly upregulated on myeloid cells in peripheral blood from lung cancer patients in comparison to normal donors." (PMID 24146823, 2013). "Finally we demonstrate that CD79a is upregulated on circulating myeloid cells from lung cancer patients, and that CD79a+ myeloid cells infiltrate human breast tumors." (PMID 24146823, 2013). "Finally, we found that neither the density nor the neighbor frequency of tumor cells with CD79a+ B cell neighbors was significantly different between recurrent and non-recurrent cases, in agreement with the inconsistent prognostic significance of B cells in lung cancer." (PMID 30651131, 2019).
atherosclerosis (26 papers, 2007 to 2025). A disease characterized by the build-up of fatty material and calcium deposition in the arterial wall resulting in partial or complete occlusion of the arterial lumen.